ABCC1 (ATP binding cassette subfamily C member 1 (ABCC1 blood group))
Diseases named in the same sentence as ABCC1 in open-access papers (continued):
Sharing a sentence is not in itself a finding about the gene and the disease.
cancer (continued). "To investigate if overexpression of ABCC1 and ABCC3 correlated functionally with drug resistance, we performed doxorubicin retention assays (n = 5) in primary cancer derived cells from the same chemotherapy treated and chemo-naive patient samples." (PMID 27171227, 2016). "Cancer cells overexpressing ABCB1 and/or ABCC1 are also resistant to Vinca alkaloids (e.g. vincristine) and colchicine." (PMID 27689338, 2016). "Further, we also investigated the expression of ABCC1 and ABCC3 in various breast cell lines ranging from immortalized to cancer cells." (PMID 27171227, 2016). "Enzastaurin has been reported to display enhanced activity in combination with various anti-cancer drugs [see e.g. 11, 13, 17, 19, 41; 58–60] including ABCB1, ABCG2, and/or ABCC1 substrates such as paclitaxel, docetaxel, erlotinib, and doxorubicin." (PMID 25749379, 2015). "The overexpression of ATP-binding cassette (ABC) transporters, particularly ABCB1, ABCC1 and ABCG2, play a key role in mediating MDR by pumping anticancer drugs out from cancer cells." (PMID 26556876, 2015). "During the process of studying its anti-cancer properties, curcumin was found to inhibit ATP-binding cassette (ABC) family members including ABCA1, ABCB1, ABCC1, and ABCG2." (PMID 24653706, 2014). "We further performed Q-RT-PCR to determine the mRNA expression levels of ABCA2, ABCC1, ABCC4, ABCD3, and ABCF2, which are the ABC transporters expressed in all of the skin samples in our semi-quantitative RT-PCR, in normal and cancer skin." (PMID 25505559, 2013). "Vandetanib inhibited the transport function of ABCC1 and ABCG2 and sensitized MDR cancer cells to substrate drugs of the two transporters." (PMID 19390592, 2009). "ABCC1, a member of the ATP-binding cassette (ABC) transporter family, plays a key function in mediating chemoresistance by facilitating the efflux of chemotherapeutic drugs from cancer cells, thereby diminishing drug effectiveness." (PMID 40362400, 2025). "Although UAs are MDR1 substrates, they do not affect the expression of ABCB1, ABCC1, and ABCC2 genes in certain cancer cells, suggesting a lower risk of developing resistance and highlighting their strong anticancer potential." (PMID 40806689, 2025). "Understanding the complex role of ABCB1, ABCC1, and ABCG2 in acquired resistance is critical for improving strategies to overcome MDR, increasing treatment efficacy, and ultimately improving outcomes for cancer patients." (PMID 38893104, 2024). "Polymorphisms were also found in other canonical cancer-related genes, including SLC37A3, BAZ1A, SRP54, MYH1 and ABCC1, but were not directly involved in MASLD pathogenesis." (PMID 38540416, 2024). "ABCC1, a multidrug resistance protein, increases drug efflux by affecting the function of the ATP binding cassette (ABC) drug efflux pump, which is also named MRP1, contributing to multidrug resistance development in cancer cells." (PMID 38726001, 2024). "The membrane transporter ABCC1 (MRP1), which confers multidrug resistance to cancer cells, was also enriched in the Panc-1 library, along with three other SLC transporters, SLC4A2, SLC30A1, and SLC12A7 (KCC4), plus the epidermal growth factor receptor EGFR and lipid transport protein ESYT2." (PMID 37295717, 2023). "It is noteworthy that ABCC1, ubiquitously expressed in mammals, has not even been mentioned in the literature in this context of cancer progression." (PMID 37047018, 2023). "In recent years, researchers have focused on understanding the mechanisms of multidrug resistance (MDR) in cancer cells and have identified the overexpression of ATP-binding cassette (ABC) transporters, including ABCC1/MRP1 and ABCC10/MRP7, as a key factor in the development of MDR." (PMID 38026953, 2023). "Based on this finding, we might hypothesize that ZNF143’s potential to change the main cancer signaling pathways may originate from CDKN1B, PIAS4, CTBP2, and ABCC1." (PMID 36675976, 2022).
cancer (continued). "Moreover, gene expression of some transporters (ABCC1, ABCC2, ABCC3, and ABCB3) was significantly elevated in recurrent cancer lesions compared with benign or malignant ovarian tissue." (PMID 35164068, 2022). "ABCC1 and ABCB1 transporters conferred resistance to multidrug resistance (MDR), an intrinsic or acquired cross-resistance toward different chemotherapeutic drugs, which has been considered as one of the primary reasons for the failure in cancer chemotherapy." (PMID 34933679, 2021). "In addition, DAUNORUBICIN was approved as an anti-cancer drug by the US Food and Drug Administration regulating SARS-CoV-2 interactors (The ABCC1 gene) and having the potential for investigation as a repurposed drug against SARS-CoV-2 infection." (PMID 33711981, 2021). "While various mechanisms are responsible for resistance of cancer cells to cytotoxic drugs, overexpression of ABC efflux proteins (e.g., P-gp/ABCB1, BCRP/ABCG2 and MRP/ABCC1) on the tumor cell membrane play a significant role in the emergence of resistance to antineoplastic drugs." (PMID 33918289, 2021). "Except for P-gp, ABCC1(also known as MRP1)and ABCG2 (also known as BCRP) have also been extensively studied, confirming their prominent roles in multidrug resistance of cancer cells." (PMID 33953682, 2021). "ABCB1 (P-glycoprotein, P-gp; multidrug resistance 1, MDR1), ABCG2 (breast cancer resistance protein, BCRP; mitoxantrone resistance, MXR), and ABCC1 (multidrug resistance protein 1, MRP1) are the most important ABC transporters and the overexpression of them render emergence of MDR in cancer cells." (PMID 32984343, 2020). "Studies investigating various cell lines, MDR cell line models, and/or clinical samples of different cancer types unambiguously showed that ABCC1 promoter methylation is not involved in ABCC1 gene regulation." (PMID 33066132, 2020). "Additionally, there is a need to expand these studies from the usual ABCB1, ABCC1, and ABCG2, to encompass all the other transporters identified as dysregulated in cancer." (PMID 32587767, 2020). "Of interest, MRP1/ABCC1 expression levels did not change when the in vitro cultures were exposed to the four anti-cancer drugs (docetaxel, vinblastine, cytarabine and methotrexate)." (PMID 30150787, 2018). "Among them, P-glycoprotein (P-gp/ABCB1), multidrug-resistant protein 1 (MRP1/ABCC1), breast cancer resistant protein (BCRP/ABCG2/MXR/ABCP), and multidrug-resistant protein 10 (ABCC10/MRP7) transporters frequently drive chemosensitive cancers to MDR." (PMID 28646911, 2017). "Since many cancer cells may develop MDR via different types of ABC transporters, we examined ABCB1, ABCG2, ABCC1, and ABCC10 in this study." (PMID 27649127, 2016). "Thus, we determined the promoter methylation patterns of ABCB1, ABCC1 and ABCG2 in 19 human cancer cell lines." (PMID 27689338, 2016). "Our data indicates that hypomethylation of the ABCC1 promoter is not cancer type-specific but occurs in cancer cell lines of different origins." (PMID 27689338, 2016). "In none of the 19 cancer cell lines the average methylation status of the ABCC1 promoter (across the eight CpGs investigated) was found to be ≥ 5%." (PMID 27689338, 2016). "We hypothesized that afatinib can effectively compete with chemotherapeutic agents for binding with ABCB1, ABCC1, or ABCG2 and thus increase drug concentrations in resistant cancer cells." (PMID 25436978, 2014). "For cisplatin/kaempferol treatments on OVCAR-3 cancer cells, the mRNA levels of ABCC1, ABCC5, and NFkB1 did not change." (PMID 20459793, 2010). "miR-7-5p/ABCC1/SLC7A5, miR-107/RAD51, miR-124-3p/ABCC4/SLC16A1/MGMT, miR-212-3p/ABCG2, miR-381-3p/GJA1 and miR-485-3p/SLC40A1 may modulate pathways that confer chemoresistance to cancer cells." (PMID 40061896, 2025).
cancer (continued). "Furthermore, immunoassays for HTC were developed to distinguish cancer cells from stromal cells using the CK8/18 antibody cocktail and to distinguish cells with a multidrug-resistant phenotype from sensitive cells using the ABCB1, ABCC1 and ABCG2 antibodies." (PMID 39337925, 2024). "Moreover, CSCs are also responsible for the drug resistance of the cancer cells by expressing multidrug resistance proteins, for example, different ATP-binding cassette (ABC) transporters, e.g., MRP1 (ABCC1) and (ABCG2), which prevent damage from drugs and therapies in cancers like leukemia." (PMID 38891090, 2024). "Considering ABCC1 is involved in the stress response, affecting intracellular GSH content and drug detoxification, this transporter could be used as a therapeutic target in cancer cells undergoing EMT." (PMID 37047018, 2023). "In addition, evidence of ubiquitous expression of ABCC1 has meant it is unlikely to be a suitable target for anti-cancer therapy." (PMID 33593355, 2021). "CCNP upregulation increased the expression of several the drug efflux transporters tested (ABCC1 p-values: A549 = 0.0181; LoVo = 0.9358; MCF7 = 0.0247), supporting the notion that CCNP may contribute to the drug resistance of cancer cells." (PMID 34604945, 2021). "However, ABCC1 and ABCC4 can also transport a wide range of substrates involved in inflammation and cellular signaling and have been shown in several different cancer types to have a role in cancer development and progression that is independent of drug resistance." (PMID 33081264, 2020). "However, the mutations in ABCB1, ABCA1, ABCC1 and ABCG2 did not affect overall cancer survival rates as determined by log-rank tests (all P-values < 0.05)." (PMID 34541464, 2020). "Therefore, we performed in vitro experiments to observe whether olmutinib could reverse MDR in cancer cells overexpressing ABCB1, ABCG2, or ABCC1 transporters." (PMID 30356705, 2018). "Therefore, we performed in vitro experiments to evaluate if olmutinib could reverse MDR in cancer cells overexpressing ABCB1, ABCG2, or ABCC1 transporters." (PMID 30356705, 2018). "In further support of the concept that hypoxia promotes cancer stemness, we found that hypoxic challenge resulted in a significant increase in the mRNA levels of ATP-binding cassette (ABC) drug transporters (i.e., ABCC1–6 as well as ABCB1), previously shown to be CSC markers." (PMID 29036915, 2017). "ABCC1 and ABCC3 may thus act as prognostic factors in many cancer subsets." (PMID 27171227, 2016). "Some key regulatory genes and proteins were modulated, such as ATP7A, ABCG2, ABCC1 and ABCB1 in response to EC-synthetic retinoids, suggesting that their expression may be under the regulation of retinoid signaling pathways with a potential role in diminishing cancer resistance and carcinogenesis." (PMID 36012706, 2022). "ABCG2 was originally identified as a multidrug transporter in multidrug-resistant cancer cell lines, in which none of the two MDR proteins known at that time (MDR1/ABCB1 and MRP1/ABCC1) was expressed." (PMID 33801813, 2021). "Although in general, the eight CpGs were unmethylated (methylation status < LOQ), some cancer cell lines (e.g. DMS114, NCI-H520 and SW1573) expressed, whereas others (e.g. GLC-4, MCF-7 and HL- 60) did not express ABCC1." (PMID 27689338, 2016). "In the present study, we showed that trametinib significantly potentiated the effects of vincristine and doxorubicin on inhibition of growth, arrest of cell cycle and induction of apoptosis in cancer cells overexpressed ABCB1, but not ABCC1 and ABCG2." (PMID 25915534, 2015). "Membrane localization of KCNJ2/Kir2.1 and MRP1/ABCC1 was observed in cancer cells, whereas no positive MRP1/ABCC1 staining was observed in normal lung alveolar epithelium." (PMID 25880778, 2015).
cancer (continued). "Trametinib significantly potentiated the effects of two ABCB1 substrates vincristine and doxorubicin on inhibition of growth, arrest of cell cycle and induction of apoptosis in cancer cells overexpressed ABCB1, but not ABCC1 and ABCG2." (PMID 25915534, 2015). "Studies with ABC transporter-overexpressing carcinoma cell models confirmed that nilotinib effectively reversed ABCB1- and ABCG2-mediated drug resistance, while showed no significant reversal effect on ABCC1- and ABCC4-mediated drug resistance." (PMID 24651611, 2014). "This, in turn, led to an elevated proapoptotic and cytotoxic activity of Dx towards a series of tumor cell lines, and also is suggested the main reason for partial circumvention of ABCC1 and ABCB1-driven resistance of cancer cells in vitro by Dx-PC-NSE, but not Dx-PC." (PMID 36986696, 2023). "ABCA1, an ABC transporter, but not ABCB1, ABCC1 or ABCC2, might be involved in the anti-cancer drug resistance observed in DU145 cells stably overexpressing embigin." (PMID 30041429, 2018). "In contrast, expression of ABCC1 (also known as MRP1), another relevant ABC transporter known to be involved in cancer cell drug resistance in various cancer entities including neuroblastoma, did not influence anti-cancer activity of SNS-032." (PMID 27517323, 2016). "In contrast, in resistant cancer cells with ABCB1/ABCC1 overexpression, afatinib can not enhance the cytotoxicity of doxorubicin, a substrate drug for both ABCB1 and ABCC1, suggesting that afatinib probably did not interact with ABCB1 or ABCC1." (PMID 25436978, 2014). "However, it has been proposed that ABCC1 and ABCC4 may play a role in the hallmarks of cancer development and progression, independent of their drug efflux capabilities." (PMID 33081264, 2020). "However recently, because of their ability to transport signaling molecules and inflammatory mediators, it has been proposed that ABCC1 and ABCC4 may play a role in the hallmarks of cancer development and progression, independent of their drug efflux capabilities." (PMID 33081264, 2020).
tumor (157 papers, 2003 to 2026). "The overexpression of ABCC1 in tumor cells has been implicated in the multidrug-resistant phenotype caused by cytotoxic drugs." (PMID 39661665, 2024). "GSEA analysis indicated that ABCC1 was associated with tumor differentiation, nod-like receptor signal pathway, and so forth." (PMID 35342392, 2022). "The GSEA results revealed that the expression of ABCC1 was associated with tumor differentiation, nod-like receptor signal pathway, resistance to the bcl2 inhibitor up, and so on." (PMID 35342392, 2022). "Disruption of the ABCB1 gene can cause a decrease in intestinal polyps and tumour incidence, while the disruption of the ABCC1 gene has been linked to reduced tumour incidence and increased tumour latency in mouse models." (PMID 33801148, 2021). "In the mouse model with the ABCC1 KO gene, the development of tumors was severely inhibited compared to mice with both alleles, suggesting the importance of the protein in tumor initiation." (PMID 32587767, 2020). "Meanwhile, the ABCC1 SNP rs35628 was associated with the pathological characteristic of tumor size (p value = 0.014), while the ABCC2 SNP rs2273697 was significantly associated with estrogen receptor status (p value = 0.013)." (PMID 31391850, 2019). "Univariate and multivariate analyses showed that expression of ABCC1 by HRS cells is associated with an increased risk of tumor progression, treatment resistance or death in CHL patients." (PMID 22871336, 2012). "Many human tumor samples also gained expression of a coordinately regulated module associated with advanced malignancy (ABCC1, FOXO3A, LIF, PIK3R1, PRNP, TNC, TIMP3 and VEGF)." (PMID 17615082, 2007). "Moreover, ABCC1 is associated with an increased risk of tumor progression, treatment resistance or death in CHL patients." (PMID 36732567, 2023). "Moreover, in the solid variant of PTC, high ABCC1 expression was associated with larger tumor size, while high ABCG2 expression was correlated with lymphovascular invasion." (PMID 35837087, 2022). "The level of circ-ABCC1 is associated with tumor growth and progression, and circCCDC66 and circ-ABCC1 levels are reduced in precursor lesions of CRC, indicating that these lncRNAs may be biomarkers for early stage CRC." (PMID 33246471, 2020). "For instance, the pro-tumorigenic action of ABCC1 might be also linked to its ability to promote the efflux of pro-inflammatory signals, which may shape the immune landscape to support the growth and response to immunotherapy of tumor cells." (PMID 39201428, 2024). "Functionally, the TRIM25-AGO2-miR-148b-5p-ABCC1 axis inhibits tumor growth and re-sensitizes NSCLC cells to chemotherapy." (PMID 42062253, 2026). "This process downregulates miR-148b-5p, a tumor-suppressive miRNA that post-transcriptionally represses ABCC1 to counteract chemoresistance." (PMID 42062253, 2026). "The transfer of exosomal circTEX2 from M2 TAMs to tumor cells significantly promoted cisplatin resistance via sponging miR-145 and indirectly targeting ATP Binding Cassette Subfamily C Member 1 (ABCC1)." (PMID 40599798, 2025). "Hyper‐expression of ABCB1, ABCG2, or ABCC1 has been documented in clinical tumor specimens to mediate MDR and poor prognosis in patients bearing malignancies in breast, liver, blood, colon, and lung." (PMID 41328326, 2025). "To further validate our findings, we examined ABCC1 protein expression in a subset of 29 OS patients using tumor samples obtained from NTUH, employing IHC staining." (PMID 39844613, 2025). "Previous studies have shown that the expression level of ABCC1 in T cells is related to drug resistance and therapeutic effect of tumor drugs." (PMID 40244859, 2025). "Our findings indicated that C1GALT1 significantly enhanced drug resistance and tumor growth in OS cells, primarily through the ABCC1 pathway." (PMID 39844613, 2025).